IL18 (interleukin 18)
Diseases named in the same sentence as IL18 in open-access papers (continued):
Sharing a sentence is not in itself a finding about the gene and the disease.
tumor (continued). "Recent studies, carried out on animal tumor models, show that different cytokines, including GM-CSF, IL-7, IL-12, IL-15, IL-18 and IL-21, are also able to limit tumor growth." (PMID 34208413, 2021). "We show that, in the majority of CRCs, tumor cells display an activated and functional caspase-1/IL-18 axis that contributes to drive a Th1/Tc1 response elicited by TILs expressing IL-18Rα." (PMID 33430344, 2021). "In triple-negative breast cancer, tumor-derived IL-18 has also been reported to increase PD-1 expression on immunosuppressive NK cells, facilitating the immune evasion of the cancer cells." (PMID 34840991, 2021). "This study aimed to determine the status of the caspase-1/IL-18 axis in tumor cells and its potential modulatory role on TILs in CRC." (PMID 33430344, 2021). "Mechanistically, the anti-tumor effect of IL-18Rαhi subset is mediated by IL-18 signaling and TCR–MHC I interaction." (PMID 34493727, 2021). "As the main effectors of NLRP3 inflammasome, IL-1β and IL-18 belong to the IL-1 superfamily and have the potential to promote an immune-suppressive tumor microenvironment." (PMID 34211462, 2021). "When considering all cases of CRC (n = 96), we found that the level of IL-18 released in tumor explant cultures was heterogeneous among CRCs and correlated with the status of aCasp1 in tumor cells." (PMID 33430344, 2021). "IL18, a pyroptosis-related inflammatory mediator, was observed to exert inflammation-dependent tumor-suppressive effects by promoting the differentiation, activity, and survival of tumor-infiltrating T cells in hepatocellular carcinoma." (PMID 35360412, 2021). "In summary, IL-18Rαhi CD8+ T cells are tumor-specific and act as short-term effector cells that drive IL-18-dependent therapeutic effect under CTXpre/CD4post." (PMID 34493727, 2021). "We found that the level of secreted IL-18 was significantly higher in the tumor than in paired normal colon." (PMID 33430344, 2021). "Anti-IL-18 treatment markedly diminished tumor suppression and survival rate in CTXpre/CD4post-experienced C57BL/6 wild-type mice." (PMID 34493727, 2021). "Researchers have suggested that AIM2 is able to activate inflammasomes, and act as a tumor suppressor by inducing IL-18 and IL-1β in GC cells." (PMID 33859277, 2021). "Together, our results strongly suggest that targeting the caspase-1/IL-18 axis can improve the anti-tumor immune response in subgroups of CRC." (PMID 33430344, 2021). "When testing IL-27 vectors and IL-18 together for potential synergy, we observed a significant reduction in tumor growth rate by day 15 relative to the control vector alone." (PMID 34209203, 2021). "In this study, HIF1α-deficient NK cells are more responsive to IL18 and hindered growth of RMA-S and LLC tumour models, showing enhanced OXPHOS and NFκB activity which correlated with increased expression of IFN-γ and Granzymes." (PMID 34090499, 2021). "IL-18 drives IFN-γ production to increase tumor immunogenicity and reinforces NK and CD4+ T cells immune responses and generates protective CD8+ T cells responses from recidivism." (PMID 33510147, 2021). "Mainly IL-1β and, to a lesser extent, IL-18 have been shown to be involved in tumor proliferation, survival, metastasis, angiogenesis, and immunosuppression, thus promoting the development and progression of cancers." (PMID 34684819, 2021). "Despite the short-term effect of IL-18Rαhi CD8+ T cells in adoptive transfer experiments, the CTXpre/CD4post-created milieu, which continuously generates the IL-18Rαhi subset, elicited profound anti-tumor efficacy in an IL-18 signal-dependent manner." (PMID 34493727, 2021). "By day 21, the 27→18 combination reduced tumor volume by ~21–52% relative to IL-27, IL-18, or vector control." (PMID 34209203, 2021). "Here the authors show that HEI3090, a chemical positive modulator of the purinergic P2RX7 receptor, promotes IL-18 mediated anti-tumor immune responses and sensitizes lung cancer to anti-PD-1 therapy in preclinical models." (PMID 33510147, 2021).
tumor (continued). "Activated GSDMD/GSDME protein leads to the formation of membrane pores and mediates the maturation and release of IL-1β and IL-18, which subsequently induces strong inflammatory response in tumor microenvironment." (PMID 34830775, 2021). "The NLRP3 inflammasome deficient mice are more susceptible to colitis-induced colorectal cancer due to reduced production of IL-18, and subsequent inactivation of tumor suppressor STAT1." (PMID 34210954, 2021). "When considering the microsatellite status, 91% of MSI CRCs and 67% of MSS CRCs were found to express the highest percentage of IL-18-positive tumor cells." (PMID 33430344, 2021). "IL-18 plays a dual role in cancer, as it promotes tumor development, progression and metastasis and it enhances anti-tumor immunity and reduces tumor growth in a matter depending on cancer progression." (PMID 34627252, 2021). "Anti-tumor T-cell related pathways were predicted as activated in IL-18- and/or IL-27-containing groups, including Th1 and TCR signaling." (PMID 34209203, 2021). "Use of cytokines like IL-2, IL-15, IL-12, IL-21 and IL-18 is considered a promising approach to induction of more efficient NK cell activation at tumor sites, while IL-15 and IL-21 can enhance NK cell cytotoxicity." (PMID 34177887, 2021). "Tumor-infiltrating NK cells are activated by direct recognition of tumor cells or by pro-inflammatory cytokines, including IL-12, IL-15 and IL-18." (PMID 34203391, 2021). "A good candidate is the inflammasome pathway that bridges innate and adaptive immunity via the caspase-1/interleukin-18 (IL-18) axis, able to elicit a T-helper/cytotoxic (Th1/Tc1) anti-tumor response." (PMID 33430344, 2021). "Hyper-activation NLRP1 inflammasome led to decreasing of tumor cells’ death and increased inflammatory microenvironment driven by IL-18 and IL-1β secretion, which has been proposed as a common mechanism of NLRP1 serving an instigator." (PMID 33658393, 2021). "In conclusion, this study showed that tumor cells of the majority of CRCs display a functional caspase-1/IL-18 axis, part of the inflammasome pathway, that can modulate the IFNγ response elicited by Th1/Tc1 TILs from the tumor microenvironment." (PMID 33430344, 2021). "AIM2 can activate inflammasomes in GC patients and act as a tumor suppressor by inducing IL-18 and IL-1β." (PMID 34680930, 2021). "IL-18 is a cytokine with pro-inflammatory properties, involved in stimulation of NK cells and Th1-biased immune responses that are crucial for anti-tumor immunity." (PMID 34616407, 2021). "These mice suffered from increased tumour burden and attenuated levels of IL-1β and IL-18, indicating that the inflammasome and its downstream cytokines play a protective role against CAC." (PMID 33918087, 2021). "In lung cancer, caspase-1 inhibition results in the reduction of IL-1β and IL-18, leading to tumour-induced immunosuppression in the lung microenvironment." (PMID 33918087, 2021). "Firstly, the level of IL-18 secreted in the tumor supernatants was compared with that measured in the supernatants of paired normal colonic mucosa (n = 10 cases)." (PMID 33430344, 2021). "In solid tumours, prolonged exposure to hypoxia induces HIF1α expression in tumour infiltrating NK cells and negatively regulates IL18-dependent NFκB activity." (PMID 34090499, 2021). "It has been reported that IL-18 exerts a significant role in tumor progression in several types of cancer." (PMID 33507690, 2021). "Another molecule is adenosine triphosphate (ATP), which can attract monocytes and DCs to tumours by a purinergic receptor P2 × 7-dependent pathway and promote the secretion of pro-inflammatory cytokines such as IL-1β and IL-18." (PMID 34281259, 2021). "Adding IL18 to the 27pepL (27pepL→18) further magnified its effectiveness, and in this treatment group the average tumor volume was stably controlled." (PMID 34209203, 2021).
tumor (continued). "In summary, tumor recognition, in cooperation with monocyte-derived IL-18, induce the expression of PD-L1 on NK cells, resulting in an enrichment in PD-L1hi NK cells that in turn limit CD8+ T cell proliferation in a PD-L1-dependent manner." (PMID 34616407, 2021). "It provokes a high production of pro-inflammatory cytokines such as interleukin (IL)-1β and IL-18 in response to the danger signals in tumour microenvironment (TME), resulting in the activation of a pro-inflammatory immune response." (PMID 33918087, 2021). "IFNγ levels were the lowest in cluster 3 despite the presence of active caspase-1 in tumor cells and high IL-18 levels." (PMID 33430344, 2021). "IL-18 neutralization, but not IL-12 or IL-15 neutralization, interfered with PD-L1 up-regulation on NK cells, suggesting that IL-18 produced during tumor-stimulation of PBMC contributes to enhance PD-L1 expression on NK cells." (PMID 34616407, 2021). "Altogether, these results identify IL-18 as a critical cytokine that contributes to PD-L1 up-regulation on tumor-experienced NK cells." (PMID 34616407, 2021). "As IL-18 is known as a driver of the Th1/Tc1 response, we assessed intraepithelial Tbet+ and CD8+ TIL densities in relation to IL-18 expression in tumor cells." (PMID 33430344, 2021). "Firstly, in the majority of CRCs (70%), tumor cells maintained a functional but aberrantly activated caspase-1/IL-18 axis compared with paired normal colonic epithelial cells." (PMID 33430344, 2021). "Downstream effectors of inflammasome signaling, IL-1β, and IL-18, have also been demonstrated to promote tumor angiogenesis 4, metastasis 5, and immune evasion 6 through paracrine and autocrine mechanisms." (PMID 34815793, 2021). "As for IL-18 being a double-edged sword, it alone promotes carcinogenesis, but when combined with NF-κb inhibitor, it exhibits an anti-tumor effect." (PMID 34691034, 2021). "We used two independent cohorts of CRC patients to assess IL-18 and caspase-1 expression by tumor cells in relation to the density of TILs and the microsatellite status of CRC." (PMID 33430344, 2021). "It has been reported that treatment with IL-18 in combination with the B7-1 costimulatory molecule resulted in the regression of melanoma with increased NK cell infiltration at the tumor tissue." (PMID 33732720, 2021). "On the other hand ASC is also recognized as an inflammasome complex adaptor molecule, which mediates inflammatory cytokines production (such as IL-1β and IL-18), mediating tumor-promoting functions." (PMID 34571825, 2021). "Together, our findings showed that the presence of an activated caspase-1/IL-18 axis in tumor cells in the majority of CRCs led to the secretion of mature IL-18." (PMID 33430344, 2021). "Conversely, an increased in NLRP1 inflammasome-mediated IL-18 production was found to induce immunosuppression in multiple myeloma tumour-bearing mice by promoting recruitment of MDSCs and hampering the cytotoxic effects of CTLs." (PMID 33918087, 2021). "In this study, we used two independent cohorts of CRC patients to assess IL-18 expression and caspase-1 activation profiles in tumor cells and studied their relationship with TILs density and microsatellite status." (PMID 33430344, 2021). "Note that AIM2 can activate inflammasomes in GC patients and act as a tumor suppressor by inducing IL-18 and IL-1β, indicating that AIM2 is an important prognostic indicator in GC patients, which is consistent with our study." (PMID 34680930, 2021). "PD-L1 expression was induced on NK cells after direct interaction with tumor cells and enhanced by monocyte-derived IL-18." (PMID 34616407, 2021). "Instead, our results indicate that IL-18 produced by monocytes represents the main factor that enhanced PD-L1 expression in tumor-stimulated NK cells." (PMID 34616407, 2021).
tumor (continued). "While nigericin induced cell death in tumor cells producing low levels of IL-1β and IL-18, increased proliferation was found in cancer cells producing, high levels of IL-1β and IL-18." (PMID 34577552, 2021). "IL‐18 is involved in tumor formation, growth, and metastasis; while in mouse models, it has been shown to be a key role in the development of liver injury." (PMID 33720453, 2021). "Tumor cells undergoing pyroptosis release IL‐1β, IL‐18, and various DAMPs, which are signals used to activate and recruit DCs or macrophages to phagocytose the pyroptotic cells and promote their maturation." (PMID 34459122, 2021). "We demonstrated that PBMC-derived factors, more precisely IL-18 produced by monocytes, plus NK cell-tumor cell contact that involves NKG2D were necessary to induce the up-regulation of PD-L1 on NK cells." (PMID 34616407, 2021). "It is shown that simultaneous assessment of the expression of the CD34 differentiation cluster and the production of IL-18 cytokine by the tumor can also be useful for determining the probability of IC-NST metastasis in RLNs." (PMID 34059727, 2021). "As an inducer of IFN-γ secretion, IL-18 has been reported to augment the activity of both NK and T cells and has antitumor ability during tumor development." (PMID 33173202, 2020). "The role of IL-18 in cancer progression, metastasis, and angiogenesis still remains controversial, but its secretion has a particular contribution to tumor environment regulation." (PMID 33015196, 2020). "This idea was strengthened by showing that using a similar PDAC model, the cytokine required, i.e., IL-18 or IL-33, depends on the site of injection, that is to say the tumor microenvironment." (PMID 33261061, 2020). "RdB/IL-12/IL-18 also increases the cytokine ratio of Th1/Th2, increases tumor infiltration of CD4+ T, CD8+ T and NK cells, and promotes differentiation of T cells expressing IL-12Rβ2 or IL-18Rα." (PMID 32050597, 2020). "Recently, Kunert at al. compared the effects of IL-12 and IL-18 production by TCR-engineered T cells on murine tumour." (PMID 32183246, 2020). "Similar to IL-1β, IL-18 production and secretion were increased in all tumor cell lines treated with LPS/Nigericin compared to untreated control." (PMID 33613529, 2020). "Because an increased expression of NLRP3, ASC, Caspase-1, IL-1β and IL-18 proteins is observed in tumor tissues from Tgfbr1/Pten 2cKO HNSCC mice, there is a rationale for testing the NLRP3 inflammasome inhibitor, MCC950 in this model." (PMID 33261061, 2020). "In mouse models, IL18-secreting CAR T cells designed to target the carcinoembryonic antigen (CEA) showed superior anti-tumor activity against solid tumors in a pancreatic cancer model." (PMID 32041222, 2020). "Without TCR stimulus, only the cells exposed to combination treatment of IL-2, IL-12 and IL-18 had an effective suppressive effect on tumor growth even at a low E:T ratio, i.e., of 0.5:1." (PMID 31947966, 2020). "This decreased expression of IL-18 was significantly correlated with the tumor size (P = 0.001) and American Joint Committee on Cancer (AJCC) stage (P = 0.013)." (PMID 33294056, 2020). "In tumor cell lines where NLRP3 activation and, IL-1β and IL-18 secretion are low, Nigericin demonstrated an anti-tumor effect." (PMID 33613529, 2020). "The inflammasome-mediated tumor suppression is proposed to be primed by IL-18, promoting hepatic NK cell maturation, and aims to target FasL-sensitive tumor cells." (PMID 33613533, 2020). "The effect of epithelial IL-18 downregulation seemed to be stronger on tumor evolution than epithelial NLRP6." (PMID 33255437, 2020). "While administration of IL-18 is responsible for tumor regression in animal cancer models, the same cytokine found in high serum concentrations, in some cancer types, demonstrates its protumor effects." (PMID 33015196, 2020).
tumor (continued). "In vivo study showed that the administration of probiotics was able to decrease multiplicity, volume and total tumour numbers, restore colon length (p < 0.05) and increase IL-18 production (p < 0.05) in tumour tissue." (PMID 32168834, 2020). "Activated NK cells secrete large amounts of IFN-γ, granulocyte-macrophage colony-stimulating factor, TNF-α, IL-18, and other factors to inhibit tumor growth." (PMID 32993787, 2020). "Specifically, systemic administration of IL-18 or IL-18 gene therapy abrogates tumor growth and prolongs the survival of tumor-bearing mice." (PMID 32708464, 2020). "Our results demonstrate that IL-12 and IL-18, when combined, constitute the most potent stimulus to enhance anti-tumor activity and induce proliferation and IFN-γ production by γδ T cells in the absence of TCR signaling." (PMID 31947966, 2020). "Anti- NTPDase1/CD39 antibodies inhibiting conversion of extracellular ATP to AMP show potent anti-tumor activity since they do not only reduce adenosine concentration but also trigger the ATP-P2X7R-NLRP3 inflammasome-IL-18 axis." (PMID 33613285, 2020). "Colitis-associated cancer was higher in NLRP3 knockout mice models; the increased tumor burden was correlated with attenuated levels of tumor IL-1β and IL-18." (PMID 31923221, 2020). "Pin1 promoted cell metastasis by increasing IL‐18 expression, and the oncogenic effect of IL‐18 was also significantly decreased in Pin1 knockdown cells, which highlighted the role of Pin1 in IL‐18‐induced tumour‐promoting effect." (PMID 32347623, 2020). "NK cells pre-exposed to IL-12, IL-15 and IL-18 accumulate in the tumor tissue and retain their anti-tumor function both in vitro and in vivo." (PMID 32762681, 2020). "Regarding RH30, at a high E:T ratio of 5:1, a significant reduction in tumor growth by γδ T cells was seen after all cytokine treatments with TCR stimulus with the combination of IL-2/IL-12/IL-18 leading to the highest reduction of impedance." (PMID 31947966, 2020). "The inflammasome controls the production of IL-1β and IL-18 and both cytokines are involved in tumor development or control." (PMID 33042810, 2020). "In tumors, IL18 staining was strong and occurred throughout the tissue, in tumor cell cytoplasm with various intensities in ovarian cells and immune cells." (PMID 31923221, 2020). "This underpins the macrophages’ key role in the tumor microenvironment as the source of IL-12 and IL-18, thus forming the crystallization point for innate and adaptive immunity." (PMID 31947966, 2020). "Tumor-derived IL-18 induces PD-1 expression on NK cells, thus allowing neutrophils to dampen their activity through binding of PD-L1 on their membrane with PD-1." (PMID 33261061, 2020). "In contrast, in tumor cell lines where NLRP3 activation and, IL-1β and IL-18 secretion are high, although Nigericin triggers initial tumor cell death, cells recover and tumors remain active." (PMID 33613529, 2020). "We found that negatively freshly isolated Vδ2+ T cells do not exhibit suppressive behavior, even after stimulation with IL-12/IL-18/IL-15 or the sheer contact with butyrophilin-3A1-expressing tumor cell lines (U251 or SK-Mel-28)." (PMID 31982940, 2020). "New signaling pathways of interferon regulatory factors 1 (IRF-1) and 2 (IRF-2) and interleukin (IL)-1 family, IL-6, IL-11, IL-18, and interferons (IFNs) have been found within tumor microenvironments." (PMID 32887217, 2020). "Extracellular ATP activates the P2X7-NLRP3-inflammasome IL-18 pathway that increases CD8+ effector T cell function within the tumor microenvironment." (PMID 32739778, 2020). "Cell-type specificity of IL-18 expression seems to confer different functional roles of this cytokine depending on its location in the tumor microenvironment." (PMID 33255437, 2020). "NLRP3 triggers innate immunity by activating caspase-1, then cleaves the inflammatory molecule IL-1β and IL-18, which induces inflammation and eliminate tumor cells." (PMID 33603669, 2020).